AIMP2 (aminoacyl tRNA synthetase complex interacting multifunctional protein 2)
Diseases named in the same sentence as AIMP2 in open-access papers (continued):
Sharing a sentence is not in itself a finding about the gene and the disease.
tumor (22 papers, 2012 to 2025). "In LV-HK2 group, high AIMP2 levels led to the retention of increased tumor volume caused by HK2 overexpression compared to the control group." (PMID 37524692, 2023). "Our findings revealed that AIMP2 was overexpressed in 24 tumor tissue types compared to normal tissue and was associated with four tumor stages." (PMID 38235352, 2023). "In this study, we investigated the expression of AIMP2 and its relationship with prognosis, Tumor Mutation Burden (TMB), and microsatellite instability (MSI) across 33 cancer types." (PMID 38235352, 2023). "Our findings indicated that AIMP2 was more highly expressed in tumor tissue than in normal tissue and was associated with various tumor stages." (PMID 38235352, 2023). "Targeting a splicing variant of AIMP2 at the interface with HSP70 also effectively suppresses tumor growth." (PMID 35501376, 2022). "Given that these pathways are critically implicated in the control of tumorigenesis, AIMP2 is expected to act as a potent tumor suppressor with broad coverage against various types of cancer." (PMID 33128014, 2020). "Furthermore, we found that AIMP2 expression is associated with cancer stage in specific tumor types." (PMID 38235352, 2023). "Moreover, AIMP2 showed significant correlations with common tumor-associated regulatory genes, such as TGF BETA SIGNALING, TNFA SIGNALING, hypoxia, pyroptosis, DNA repair, autophagy genes, and ferroptosis-related genes." (PMID 38235352, 2023). "Furthermore, we observed an association between AIMP2 expression and multiple tumor stages, including ACC, BRCA, LUAD, and THCA, respectively." (PMID 38235352, 2023). "Single-cell analysis revealed homogeneous AIMP2 expression in tumor tissues, particularly in astrocyte-like cells, suggesting a mechanistic link to tumor angiogenesis." (PMID 40874786, 2025). "This analysis revealed a homogeneous expression pattern of AIMP2 across tumor tissues, with expression levels ranging from low or near-zero expression to high but lacking distinct regions of co-localization." (PMID 40874786, 2025). "Immunohistochemistry revealed that AIMP2 was highly expressed in tumor tissue and exhibited low expression in normal tissue." (PMID 38235352, 2023). "In conclusion, our first pan-cancer analysis of AIMP2 revealed differential expression between tumor and normal tissues." (PMID 38235352, 2023). "To investigate the relationship between AIMP2 expression and 33 tumor immune-related genes, we performed gene co-expression analysis in this study." (PMID 38235352, 2023). "Aminoacyl tRNA synthetase complex interacting with multifunctional protein 2 (AIMP2), a multifunctional tumor suppressor, can prompt apoptosis and repress cell stemness." (PMID 37524692, 2023). "AIMP2, a multifunctional tumor suppressor, was proposed as a potential downstream protein of HK2 by IP and mass spectrometry." (PMID 37524692, 2023). "In conclusion, our pan-cancer analysis identified differential expression of AIMP2, suggesting its potential importance in tumor immunity and its promise as a potential prognostic marker, especially for BRCA." (PMID 38235352, 2023). "The mechanism of AIMP2 as a potent tumor suppressor is related to the triggering of growth-arrest signaling in transforming growth factor-beta, which is caused by the enhancement of the ubiquitin-mediated degradation of the FUSE-binding protein." (PMID 34679529, 2021). "The implication of the AIMP2-DX2/AIMP2 expression ratio for OS and tumor-node-metastasis stage was further investigated in other cancer types." (PMID 33128014, 2020). "Previous studies have shown that DX2 compromises the tumor suppressive activity of AIMP2 and promotes tumor progression." (PMID 32471182, 2020). "Among the AIMPs, AIMP2 works as a potent tumor suppressor and induces growth arrest by transforming growth factor-β (TGF β) signaling via ubiquitin-mediated degradation of FUSE-binding protein (FBP) and downregulation of c-myc." (PMID 32549310, 2020).
tumor (continued). "AIMP2 heavily features the profile of an oncogene, which is unexpected considering the abundant literature on anti-tumor functions of the AIMP2 protein." (PMID 33266490, 2020). "This implies that the tumor may rely on angiogenesis-driven pathways for survival, potentially explaining the observed enhanced response of AIMP2-high tumors to antiangiogenic therapies with a more uniform therapeutic effect across the tumor." (PMID 40874786, 2025). "Given that AC-like cells are characterized by EGFR amplification/overexpression, which regulates VEGF expression, the enrichment of AIMP2 in this subtype may explain a possible mechanistic link between AIMP2 expression and the tumor's angiogenic profile." (PMID 40874786, 2025). "It remains to be determined whether changes in AIMP2 expression actively contribute to disease phenotypes or are secondary to broader dysregulation in tumor biology." (PMID 40874786, 2025). "We next examined the role of another host protein candidate, the 35 kDa AIMP2, which is a tumor suppressor protein that is part of a multi-tRNA synthetase complex and is proposed to act as a scaffold as well as a regulator of signaling pathways such as the NFκB pathway and apoptosis." (PMID 38953667, 2024). "A positive correlation between AIMP2 expression and tumor stage in ACC, BRCA, and LUAD was observed, which could inform immunotherapy selection for patients with different stages of these cancers." (PMID 38235352, 2023). "In conclusion, our pan-cancer analysis suggests that AIMP2 may play a crucial role in tumor immunity and could serve as a potential prognostic marker, particularly in BRCA." (PMID 38235352, 2023). "Despite its abnormal expression in various tumor types, the specific functions and effects of AIMP2 on tumor immune cell infiltration, proliferation, and migration remain unclear." (PMID 38235352, 2023). "Moreover, AIMP2 was found to be significantly correlated with common tumor-related regulatory genes, such as TGF BETA SIGNALING, TNFA SIGNALING, hypoxia, pyroptosis, DNA repair, autophagy genes, and ferroptosis-related genes." (PMID 38235352, 2023). "Our study establishes that aberrant AIMP2 expression occurs in numerous tumor types." (PMID 38235352, 2023). "Moreover, our study examined the relationship between AIMP2 gene expression and common anti-tumor drugs using the CellMiner database, revealing that high AIMP2 expression is predicted to correlate with tolerance to multiple anti-tumor drugs." (PMID 38235352, 2023). "Additionally, we performed gene co-expression analysis to investigate the relationship between AIMP2 expression and 33 tumor immune-related genes, including MHC, immune activators, immune suppressors, chemokines, and chemokine receptor proteins." (PMID 38235352, 2023). "In MHCC97H LV-HK2 and LV-RFP cells after IR, AIMP2 overexpression decelerated tumor growth." (PMID 37524692, 2023). "Furthermore, AIMP2 expression was associated with TMB, MSI, and immune cell infiltration across multiple cancer types, with its impact on tumor immunity varying among tumor types." (PMID 38235352, 2023). "It is reported that AIMP2 usually shows tumor-suppressive activities." (PMID 32709848, 2020). "While aminoacyl-tRNA synthetase-interacting multifunctional protein 2 (AIMP2) is a tumor suppressor, its exon 2-depleted splice variant (AIMP2-DX2 or shortly DX2) is highly expressed in human lung cancer, and the ratio of DX2 to AIMP2 increases according to the progression of lung cancer." (PMID 32549310, 2020). "All this evidence suggests that AIMP2 is a tumor suppressor." (PMID 29854811, 2018). "Two of these genes (EIF2AK1 and AIMP2) have tumor-suppressing functions." (PMID 22585707, 2012).
tumor (continued). "Existing studies suggest that AIMP2 may function as a multifaceted tumor suppressor." (PMID 38235352, 2023). "Future studies should aim to elucidate the mechanistic role of AIMP2 in GBM biology, particularly in the context of angiogenesis and tumor progression." (PMID 40874786, 2025). "The findings revealed notable enrichment of AIMP2 and IYD in tumour cells, whereas QARS1 was enriched in immune cells." (PMID 40493339, 2025). "To further investigate the molecular mechanisms of AIMP2 in pan-cancer, we employed GSVA to score all tumor samples and subsequently divided them into high and low-expression groups based on the median gene expression." (PMID 38235352, 2023). "The dissociated AIMP2 translocated to the nucleus and bound to Smad ubiquitin regulatory factor 2 (Smurf2), thereby enhancing the ubiquitination of FBP and inhibiting tumor formation." (PMID 32709848, 2020). "Specifically looking at the cytoplasmic aaRS members, the genes that are preferentially amplified across most tumor types are TARS1, GARS1, MARS1, AIMP2, and AIMP3/EEF1E1." (PMID 33266490, 2020). "Remarkably, specific aaRS genes do show a DNA profile reminiscent of an oncogene (e.g., GARS1, AIMP2, and YARS2) or tumor suppressor (e.g., NARS1, QARS1, LARS2, and RARS2)." (PMID 33266490, 2020). "AIMP2 was homogenously distributed across GBM tumor tissues without forming localized clusters or regions of concentrated expression." (PMID 40874786, 2025). "Interestingly, when AIMP2 is dissociated from the MSC, it can act as a multifaceted tumor suppressor, controlling the p5319, tumor necrosis factor (TNF)-α20, transforming growth factor (TGF)-β21,22, and Wnt23 pathways depending on the cell context." (PMID 35546148, 2022). "The expression of AIMP1, AIMP2, and AIMP3 was downregulated in gastric and colorectal cancer, which might result in their inactivation of tumor suppressor functions and tumor development." (PMID 32709848, 2020). "The effects of pyrimethamine on endogenous DX2 or AIMP2 were also analyzed by immunoblotting, and the specific decrease of DX2, not AIMP2, protein level was frequently observed in the pyrimethamine-treated tumor tissues." (PMID 32549310, 2020). "The widespread expression of AIMP2 may have significant therapeutic implications for antiangiogenic treatments as it indicates that the entire tumor—not just isolated regions—may rely on angiogenesis-driven survival mechanisms." (PMID 40874786, 2025). "However, since DX2 seems to act only when extra amount of AIMP2 is present, induced in a specific stress condition, logically its overexpression is non-oncogenic and it barely disturbs the tumour suppressive function of AIMP2 in normal condition." (PMID 38172953, 2024).
cancer (16 papers, 2012 to 2025). A tumor composed of atypical neoplastic, often pleomorphic cells that invade other tissues. "Survival analysis indicated that AIMP2 expression was strongly correlated with overall survival (OS) in certain cancer patients, with high AIMP2 expression linked to poorer prognosis in five cancer types." (PMID 38235352, 2023). "Survival analysis revealed a strong association between AIMP2 expression and overall survival (OS) in certain cancer patients, where high AIMP2 expression correlated with worse prognosis in five types of cancer." (PMID 38235352, 2023). "Our analysis indicated that high AIMP2 expression is associated with increased resistance to multiple anti-cancer drugs." (PMID 38235352, 2023). "Most importantly, reduced AIMP2 expression level in Aimp2 heterozygous mice is associated with increased susceptibility to cancer in the colon and other tissues as well." (PMID 22585707, 2012). "Our findings revealed a strong association between AIMP2 expression and immune infiltration, with 14 cancers significantly correlated with M0 macrophages, 10 cancers significantly correlated with M2 macrophages, and 8 cancers significantly correlated with M1 macrophages." (PMID 38235352, 2023). "This study investigated the association between AIMP2 expression and TMB and MSI across various cancers." (PMID 38235352, 2023). "Our study demonstrated that the AIMP2 gene is highly expressed in 24 types of cancer, with IHC analysis corroborating this trend at the protein level in BRCA." (PMID 38235352, 2023). "We examined the relationship between AIMP2 gene expression and the sensitivity to commonly used anti-cancer drugs using the CellMiner database." (PMID 38235352, 2023). "Our study demonstrated that AIMP2 expression correlates with TMB in eight cancer types and with MSI in five cancer types." (PMID 38235352, 2023). "In the majority of cancer tissues, AIMP2 expression levels were higher than those in normal tissues." (PMID 38235352, 2023). "The ratio of AIMP2-DX2 to AIMP2 was positively correlated with the cancer stage, while it was negatively correlated with patient survival." (PMID 34660690, 2021). "Considering the ICGC/TCGA analysis that several cancer pathways showed a positive correlation with the ratio of AIMP2-DX2/AIMP2 in AML, we extended our analysis using ML-1 AML cells." (PMID 33128014, 2020). "DX2 counteracts the anti-cancer activities of the full-length AIMP2 protein by competing with the normal binding partners of AIMP2." (PMID 33266490, 2020). "Additional studies with a larger patient number will be able to delineate clinical implications of the AIMP2-DX2/AIMP2 expression ratio in these cancers." (PMID 33128014, 2020). "Next, we utilized these cells to verify the result of the ICGC/TCGA database analysis that AIMP2-DX2/AIMP2 expression ratio correlates with major cancer signaling pathways in AML." (PMID 33128014, 2020). "Recent studies show that AIMP2 can be departed from the complex to inhibit the development of cancers, via interacting with damaged DNA or mediating ubiquitin of substrates." (PMID 29854811, 2018). "Although there are so many reports on the roles of miR-95 in cancer cell growth, our current study is the first to demonstrate a regulatory role of miR-95 in myogenic development, and identified AIMP2 as a target gene for miR-95." (PMID 29340059, 2017). "Our results demonstrated that AIMP2 plays a crucial role in cancer immunity." (PMID 38235352, 2023). "Considering existing research and our findings, we hypothesize that tumors with high AIMP2 expression and elevated TMB and MSI levels may exhibit improved prognosis following ICI treatment in cancers where AIMP2 expression positively correlates with TMB." (PMID 38235352, 2023).
cancer (continued). "The specific role of AIMP2 in each cancer warrants further investigation, as its expression levels may result in different prognostic outcomes." (PMID 38235352, 2023). "Moreover, Kaplan-Meier survival analysis results indicated that high AIMP2 expression correlated with poorer OS in five cancer types: ACC, BLCA, BRCA, HNSC, and UCEC." (PMID 38235352, 2023). "We analyzed the expression of AIMP2 in 33 human cancers using TCGA and GTEx datasets, respectively." (PMID 38235352, 2023). "In particular, even normal cells can express a low level of AIMP2-DX2, indicating that the percentage of cancer cells in the population may affect the expression ratio of AIMP2-DX2/AIMP2." (PMID 33128014, 2020). "In Kyoto Encyclopedia of Genes and Genomes pathway gene set analysis, AIMP2 and AIMP3 expressions showed significant correlation with angiogenesis gene set expressions in 20 of 33 and 21 of 33 TCGA cancers, respectively." (PMID 40874786, 2025). "AIMP2 and AIMP3 expressions showed significant correlation in 24 of 33 and 21 of 33 TCGA cancers in Panther pathway analysis, respectively." (PMID 40874786, 2025). "Genes such as PARP1, NAMPT, AIMP2, MCL1, and TOMM20 exhibited widespread amplifications of CNVs in multiple cancers, while genes like RNF146, GPX4, ESR1, CUL4A, and PTEN showed widespread deletions." (PMID 38499384, 2024). "Therefore, we hypothesize that AIMP2 may play a critical role in cancer initiation and progression." (PMID 38235352, 2023). "Of 23 types of cancer in the ICGC/TCGA database, AIMP2-DX2/AIMP2 expression ratio was most strongly correlated with major cancer pathways, such as the MAPK signaling pathway, in AML." (PMID 33128014, 2020). "Specific aaRSs that are differentially upregulated across many cancer types include TARS1 (n = 23), DARS2 (n = 22), GARS1 (n = 21), YARS2 (n = 21), EPRS1 (n = 20), AIMP2 (n = 19), and FARSA (n = 18)." (PMID 33266490, 2020). "AIMP2 (Aminoacyl-tRNA synthetase interacting multifunctional protein 2, also known as p38/JTV-1), one isoform of the three AIMPs, is involved in cancer development." (PMID 29854811, 2018). "This suggests that AIMP2 expression levels may influence TMB and MSI in cancer, thereby affecting a patient's response to immune checkpoint suppression therapy and providing a novel reference for immunotherapy prognosis." (PMID 38235352, 2023). "Here, we not only summarize the biological functions of AIMP1, EMAP II, AIMP2, AIMP2-DX2, and AIMP3, but also focus on their emerging roles in regulating tumorigenesis, suggesting that their thorough study may provide new insights into cancer treatment." (PMID 32709848, 2020). "Interestingly, AIMP2-lacking exon 2 (AIMP2-DX2), a tumorigenic factor, is often upregulated in many cancers." (PMID 34660690, 2021).
infection (3 papers, 2016 to 2024). The state of being infected such as from the introduction of a foreign agent such as serum, vaccine, antigenic substance or organism. "Modification of the same M1 K242 by a small ubiquitin-like modifier (SUMO) is crucial for nuclear export of newly produced vRNPs and viral morphogenesis, which could explain AIMP2-mediated enhancement of IAV replication at late steps of infection." (PMID 27783058, 2016). "Aminoacyl-tRNA synthase complex-interacting multifunctional protein 2 (AIMP2) is a cellular protein that promotes vRNPs’ nuclear export and replication at the late steps of infection." (PMID 34835115, 2021). "To determine whether the cleaved fragments have a role in infection, we expressed GFP-tagged N-terminal or C-terminal AIMP2 fragments in HeLa cells infected with CVB3." (PMID 38953667, 2024). "AIMP2 promotes nuclear export of vRNPs and IAV replication at late steps of infection." (PMID 27783058, 2016).
neurodegenerative disease (3 papers, 2014 to 2022). A disorder of the central nervous system characterized by gradual and progressive loss of neural tissue and neurologic function. "Based on the longevity-related genes (i.e., Akt1, NRF1, parkin, and AIMP2), potentially effective therapeutics might be exploited for the rejuvenation and cure of age-associated neurodegenerative diseases." (PMID 36711211, 2022). "Another important connection between ARS function and neurodegenerative disease reported recently is the linkage between the aminoacyl-tRNA synthetase complex interacting multifunctional protein-2 (AIMP2, also referred to as p38) and familial Parkinson's disease." (PMID 24917879, 2014).
hematologic cancers (1 paper, 2020). "More importantly, subclassification of hematologic cancers based on their AIMP2-DX2/AIMP2 expression ratios can be used to design patient-specific treatment strategies." (PMID 33128014, 2020). "Applying our image-based quantification tool, we subclassified seven hematologic cancers based on their AIMP2-DX2/AIMP2 expression ratios." (PMID 33128014, 2020).